PRXL2C (peroxiredoxin like 2C)
Description:
May positively regulate ERK1/2 signaling and AKT1 activation leading to HIF1A up-regulation with an increased expression of glycolysis genes and enhanced glycolysis.
Synonyms: AAED1; C9orf21
Tractability: PROTAC: ubiquitination databases record sites on it.
Gene: Protein-coding gene on chromosome 9 (96,639,577 to 96,655,337, reverse strand). Ensembl gene ENSG00000158122.
Gene Ontology:
Biological process: positive regulation of ERK1 and ERK2 cascade; positive regulation of glycolytic process
Genetic constraint (gnomAD): Loss-of-function variants: 38 observed, 20.56 expected, observed/expected ratio (o/e) 1.85, 90% interval 1.38 to 1.97. The upper end of that interval is the gene's LOEUF score, 1.97, which puts it in group 6 of 6, group 1 being the genes least tolerant of losing a copy. Missense variants: 293 observed, 243.48 expected, observed/expected ratio (o/e) 1.2, 90% interval 1.09 to 1.33. Synonymous variants: 98 observed, 90.97 expected, observed/expected ratio (o/e) 1.08, 90% interval 0.91 to 1.27.
Homologues: Orthologues: chimpanzee PRXL2C (99% identical), rabbit PRXL2C (90% identical), dog PRXL2C (88% identical), mouse Prxl2c (88% identical), pig PRXL2C (82% identical), macaque PRXL2C (81% identical), rat Prxl2c (75% identical), tropical clawed frog prxl2c (53% identical), zebrafish prxl2c (53% identical).
Diseases named in the same sentence as PRXL2C in open-access papers:
PRXL2C is named in the same sentence as 1 disease in open-access papers, as found by Europe PMC text mining. Sharing a sentence is not in itself a finding about the gene and the disease.
PRXL2C shares sentences with these, for which no sentence is quoted: gastric cancer (1 paper).